ALB (albumin)
Diseases named in the same sentence as ALB in open-access papers (continued):
Sharing a sentence is not in itself a finding about the gene and the disease.
Hypocalcemia (continued). "In addition to hypocalcemia, decreased plasma albumin and active vitamin D metabolites are commonly seen in TB patients." (PMID 37510958, 2023). "A total of 11 risk factors associated with postoperative hypocalcemia were identified in these 13 studies, including preoperative serum calcium, phosphorus, ALP, iPTH, ALB, pruritus, age, weight of resected glands, body weight, male sex, and volume of resected glands." (PMID 35285377, 2022). "Hypocalcemia was defined as albumin-adjusted total calcium below 8.4 mg/dl." (PMID 36698873, 2022). "It must be considered whether uncorrected serum calcium levels, albumin-corrected serum calcium levels or ionized calcium levels are the basis for the different studies to define hypocalcaemia." (PMID 36050906, 2022). "In defining hypocalcaemia in pregnancy, authors have used total or albumin corrected values." (PMID 33152011, 2020). "However, after correcting the calcium for albumin, only one patient, i.e., 0.56% of the entire study demonstrated true hypocalcemia." (PMID 32587615, 2020). "After correcting the calcium to albumin, zero incidence of true hypocalcemia was reported." (PMID 32587615, 2020). "Thus, total calcium concentration should always be corrected by albumin level during the investigation of hypocalcemia (A)." (PMID 29694629, 2018). "Low albumin concentrations may inaccurately indicate hypocalcemia, but the ionized calcium fraction is normal." (PMID 29694629, 2018). "Furthermore, the pre-treatment levels of albumin-adjusted serum calcium and creatinine are the strongest predictors in denosumab-related hypocalcemia, but sex, age, vitamin D, PTH, alkaline phosphatase, or prior osteoporosis treatment do not have predictive value." (PMID 40149708, 2025). "In patients with hypocalcemia (serum calcium corrected for albumin < 8 mg/dL), the following tests are recommended to complete the diagnosis: parathormone, serum calcium corrected for albumin value, serum phosphorus, serum magnesium, creatinine and 25OH-vitamin D, 24 h calciuria." (PMID 35407442, 2022). "Introduction of sodium glycerophosphate in the PN solution (PO4 80 mg/kg/day) resulted in a prompt decrease in Ca concentrations to 10 mg/dl within 24 h, with transient symptoms of hypocalcaemia (ionized Ca 3.4 mg/dl), which could be in part favored by contemporary infusion of albumin." (PMID 34233724, 2021). "However, after correcting the calcium for albumin, hypocalcemia incidence was 0.56% (n = 1)." (PMID 32587615, 2020). "In the FREEDOM study, an albumin-corrected serum calcium level of <2.0 mmol/L (<8.0 mg/dL), corresponding to a CTCAE grade ≥2, was used as cutoff for hypocalcemia." (PMID 39243386, 2025). "Serum total albumin-adjusted calcium level was significantly lower in the VDD group (7.71 ± 0.5 vs. 8.16 ± 0.4 mg/dL, p < 0.01), and the incidence of symptomatic hypocalcemia was significantly higher in the VDD group (43% vs. 9%, p=0.01)." (PMID 32774362, 2020). "No cases of moderate or severe hypocalcaemia (serum calcium corrected for albumin < 8 mg/dL) or acute transplantation rejection were observed during the clinical follow-up in any of the two groups." (PMID 38730099, 2024). "Severe hypocalcemia (<7.5 mg\dl) occurred in 5 patients (2%) after ZOL and 8 patients (6%) after Dmab treatment (P = .06) using calcium levels that had been corrected for serum albumin." (PMID 39416429, 2024). "When assessed according to the serum calcium levels (without albumin adjustment), the incidence of grade ≥ 1 and ≥ 3 hypocalcemia were 69.3% (n = 363) and 10.7% (n = 56), respectively." (PMID 38360579, 2024). "The proposed mechanism was that the lipolysis of adipose tissue and the release of FFAs may contribute to hypocalcaemia by the local formation of calcium salts, FFA-albumin complexes binding calcium and damage of the parathyroid function." (PMID 35637538, 2022).
Hypocalcemia (continued). "We presented the prevalence for total crude, albumin-corrected and ionised hypocalcaemia in late pregnancy but failed to hormonally explore women with ionised hypocalcaemia to find full explanations." (PMID 35584129, 2022). "Although all-grade hypocalcemia events were noted with these drugs, no further details like persisting or transient hypocalcemia or corrected calcium levels for albumin were not provided." (PMID 32587615, 2020). "None of the patients had hypocalcemia (serum calcium corrected for albumin < 2.10 mmol/l) and 69 patients had hypercalcemia with a corrected serum calcium of > 2.55 mmol/l." (PMID 32725291, 2020). "Evaluate the sensitivity, specificity, positive and negative predictive value of using albumin-corrected calcaemia to define hypocalcaemia in late pregnancy considering ionised hypocalcaemia as a gold standard." (PMID 33152011, 2020). "It is conceivable that low albumin also predicted hypocalcemia since total calcium rather than ionized calcium was analysed." (PMID 31848883, 2020). "Plasma PTH levels increased in the absence of a significant reduction of serum albumin-corrected calcium levels, and none of the patients experienced hypocalcemia or fragility clinical fractures." (PMID 33204260, 2020). "Despite the fact that they considered a lower cut-off point (less than 8.0 mg/dl) to define hypocalcaemia among their pregnant women, they did not concomitantly normalise the measured calcium concentrations by serum albumin." (PMID 31697767, 2019). "As previously reported, serum albumin-corrected calcium decreased though none of the patients experienced hypocalcemia, while plasma PTH levels tended to increase." (PMID 25873952, 2015). "Finally, hypocalcemia may also occur in DKA due to increased urinary excretion and metabolic acidosis, which leads to greater calcium binding to albumin." (PMID 40282004, 2025). "In this study, we reported the incidence of hypocalcemia by renal function in patients treated with denosumab for bone metastases of solid tumors and confirmed the importance of albumin adjustment in the assessment of hypocalcemia, independent of renal function." (PMID 38360579, 2024). "Therefore, we evaluated the incidence of hypocalcemia, according to the renal function level and with and without albumin adjustment, in patients treated with denosumab for bone metastases from solid tumors." (PMID 38360579, 2024). "Indeed, we identified a large discrepancy between the incidence of grade ≥ 1 hypocalcemia with and without albumin adjustment, which was 69.3% and 35.7%, respectively." (PMID 38360579, 2024). "However, the prevalence of total hypocalcaemia in late pregnancy among apparently healthy women in NHD is as high as 61.64% and 56.70% depending on whether total crude or total albumin-corrected calcium concentrations are considered, respectively." (PMID 35584129, 2022). "Interestingly, some prospective studies reported a high incidence of hypocalcemia in patients on ICI, but this might have been biased by fluctuations in albumin level and acute kidney insufficiency." (PMID 36149449, 2022). "Finally, in those with frequent albumin infusions, the systemic iCa checks every 6 h allow for adjustments to the QCa without any development of clinically concerning ionized hypocalcemia." (PMID 34215201, 2021). "Thus, the higher reported incidence of hypocalcemia in these trials is likely due to the reporting of serum calcium without albumin correction." (PMID 32587615, 2020). "Total hypocalcemia could have also resulted from hypoproteinemia; however, serum total protein and albumin concentrations were not statistically different between foal groups, making it an unlikely cause of hypocalcemia in the septic foals of this study." (PMID 26046642, 2015). "In particular, given that hypocalcemia is one of the most common adverse effects of TPE, the absence of calcium in 5% isotonic albumin solutions cannot be overlooked." (PMID 41299855, 2025).
Hypocalcemia (continued). "The percentage of patients with hypocalcemia was much higher and similar to the KEYNOTE-189 and CHECKMATE-067 trials when serum calcium values without albumin correction were calculated." (PMID 36672478, 2023). "The percentage of patients with hypocalcemia is much higher and similar to the KEYNOTE-189 and CHECKMATE-067 trials when serum calcium values without albumin correction are used." (PMID 32587615, 2020). "Laboratory testing should confirm a low albumin-corrected total serum calcium level or a low ionized calcium levels and low PTH on at least two occasions (emergent care for hypocalcemia should not be delayed and does not require two test results for confirmation of hypocalcemia)." (PMID 30540559, 2019).
end-stage renal disease (112 papers, 2005 to 2026). "A previous study reports that a serum albumin level <3.7 g/dL was independently associated with poor composite renal outcomes (predialysis mortality and end-stage renal disease) in patients with CKD-ND." (PMID 34150871, 2021). "Previous reports on the renoprotective effect of SGLT2 inhibitors have mainly analyzed the combined renal endpoints, including end-stage renal failure, creatinine doubling and death from renal disease, or a decrease in urinary albumin." (PMID 37773087, 2023). "For instance, in the South Korean study, end-stage renal disease was defined by diagnostic code, while in our study, we defined CKD by values of CKD-EPI glomerular filtration rate <60 ml/min/1.73 m2 and/or an albumin/creatinine ratio >30 mg/g." (PMID 35118094, 2021). "The comparative predictive performance of spot urine ratios and 24 hr urine collections (of albumin or protein) for the clinical outcomes of CKD progression, end-stage renal disease (ESRD), and mortality in Asians is unclear." (PMID 25649135, 2015).
glomerulosclerosis (110 papers, 2011 to 2026). A hardening of the kidney glomerulus caused by scarring of the blood vessels. "As expected, adriamycin (ADR) treatment caused severe glomerular sclerosis, elevated urinary albumin excretion, and reduced body weight compared with the control group (CON)." (PMID 41285716, 2025). "Edoxaban, an oral factor Xa inhibitor, and PAR2 deficiency improved glomerulosclerosis and urinary albumin excretion, and this was accompanied by a decrease in renal-inflammation–fibrosis-related markers in this model." (PMID 40002827, 2025). "In the present study, the decreased podocyte density in LPD diabetic offspring was associated with increased albumin excretion and glomerulosclerosis." (PMID 36695822, 2023). "These macrophages also were negatively correlated with serum albumin level (r = −0.331, P = 0.014), while positively associated with complement 3 (C3) deposition (r = 0.300, P = 0.026) and the severity of glomerulosclerosis (r = 0.276, P = 0.041)." (PMID 34095170, 2021). "The eNOS KO mice showed exacerbated glomerular injury with significantly increased serum creatinine, a percentage of glomerular sclerosis, urinary albumin excretion, and inflammasome-associated cytokine gene expression." (PMID 34502177, 2021). "Correlation analysis showed that the total macrophage count was negatively associated with serum albumin level, while positively associated with C3 deposition and the severity of glomerular sclerosis." (PMID 34095170, 2021). "Urinary albumin excretion causes glomerular diseases such as podocyte injury, glomerulosclerosis by mesangial hypertrophy, and dysfunction of vascular endothelial cells." (PMID 34940691, 2021). "Diabetic nephropathy (DN), characterized by renal inflammation, urinary albumin, decreased glomerular filtration rate, glomerulosclerosis and tubulointerstitial fibrosis, is a leading cause of end-stage renal disease (ESRD)." (PMID 30926764, 2019). "Urine albumin-to-creatinine ratio (r = 0.49, p = 0.03), mesangial index (r = 0.64, p = 0.001), and glomerulosclerosis score (r = 0.51, p = 0.02) were associated with SAA3 immunostaining scores across mouse groups." (PMID 30763329, 2019). "The treatment of D-OVX rats with progesterone attenuated diabetic-associated increases in the urinary albumin to creatinine ratio, glomerulosclerosi and the expression of profibrotic and angiogenic factors (TGF-β, Fibronectin and VEGF-A)." (PMID 26583047, 2015). "Additionally, PAS and Masson's trichrome staining revealed that METTL3 deficiency significantly reduced STZ‐induced glomerular sclerosis and extracellular matrix accumulation, alongside a decrease in the albumin/creatinine ratio (UACR)." (PMID 40421968, 2025). "In the kidneys, chronic inflammation leads to glomerulosclerosis and interstitial fibrosis inducing a loss of glomerular filtration surface area and impaired tubular function, decreased filtration capacity, and increased leakage of albumin into the urine." (PMID 41302171, 2025). "In addition, albumin sequestration within podocytes is associated with podocyte loss and glomerulosclerosis." (PMID 24924335, 2014). "Lysosomal dysfunction impairs albumin degradation, escalates cytokines, and drives glomerulosclerosis, directly connecting protein overload to scarring." (PMID 41009556, 2025). "The AKI group also exhibited higher baseline levels of serum uric acid and SCr, lower serum albumin levels and eGFR, higher 24 h UPr levels, higher rates of glomerulosclerosis and crescent formation, and a higher chronicity index." (PMID 40256734, 2025). "Impaired lysosomal degradation in podocytes leads to albumin accumulation, cytokine production, and glomerulosclerosis." (PMID 41009556, 2025). "Lysosomal dysfunction in podocytes impairs albumin processing, increases cytokine production and promotes glomerulosclerosis." (PMID 41009556, 2025).
glomerulosclerosis (continued). "Overall, dogs with glomerulosclerosis are older, and dogs with membranous nephropathies have lower serum albumin concentrations than other proteinuric dogs, although substantial overlap exists in clinicopathological features." (PMID 40692207, 2025). "Cat-S or PAR2 inhibitors ameliorated albuminuria and glomerulosclerosis in type 2 diabetic db/db mice, as well as albumin leakage into the retina and other structural markers of diabetic retinopathy." (PMID 40002827, 2025). "NCOA3 knockout aggravated podocyte injury, urinary albumin excretion, and glomerulosclerosis, and led to decreased autophagy in the DKD model." (PMID 38483947, 2024). "PAN-treated rats exhibited a significant increase in urine albumin excretion and serum creatinine, as well as the marked glomerulosclerosis easily seen in the PAS-stained sections." (PMID 39791723, 2024). "On the other hand, upregulated renal TF expression was also positively correlated with the increased concentration of urinary albumin excretion, glomerular fibrin deposition, and glomerulosclerosis." (PMID 38143793, 2023). "They worsen renal fibrosis, tubular damage, and glomerular sclerosis in addition to raising urine albumin excretion." (PMID 38239986, 2023). "Urinary albumin: 100–200 μg/day; kidney pathology showed severe glomerulosclerosis, tubulointerstitial fibrosis, and GBM thickening." (PMID 38143793, 2023). "Urinary albumin was 186 ± 20 μg/day; kidney pathology exhibited mesangial expansion, glomerulosclerosis, and GBM thickening." (PMID 38143793, 2023). "After 20 weeks, the KO STZ group had lower levels of urine albumin excretion, glomerular sclerosis, and interstitial fibrosis than those of the WT STZ group." (PMID 37845302, 2023). "RAGE vaccination in db/db mice attenuated urinary albumin excretion, podocyte injury, and glomerular sclerosis, as well as reduced ICAM–1 and VCAM–1 production." (PMID 37007029, 2023). "The increased urinary albumin was involved in the occurrence of epithelial casts and glomerulosclerosis in the kidney." (PMID 37222582, 2023). "Alport mice exhibited glomerulosclerosis, tubular dilation, the excretion of albumin into tubular lumens, and infiltration of inflammatory cells, especially mononuclear cells." (PMID 35271660, 2022). "Compared to the vehicle control mice, Ac-FLTD-CMK-treated MRL/lpr mice had a lower urine albumin-creatinine ratio, a lower serum creatinine concentration, reduced glomerulosclerosis and CD3, CD4 and CD68 positive cell infiltration." (PMID 34867948, 2021). "Experimental models have shown ruboxistaurin, a PKCβ inhibitor, preserves kidney function by reducing urinary albumin excretion, reducing mesangial expansion and glomerulosclerosis and normalising tubulointerstitial fibrosis." (PMID 33976959, 2021). "Renal injury (albumin excretion, glomerulosclerosis, blood urea nitrogen (BUN)) was measured as a hemodynamic function (glomerular filtration rate (GFR), mean arterial pressure (MAP)) in conscious mice." (PMID 32652896, 2020). "Urinary L-FABP levels were significantly correlated with both urinary albumin (ρ = 0.83, p < 0.0001) and glomerular sclerosis scores (ρ = 0.68, p < 0.05)." (PMID 32405506, 2020). "Deletion of Sirt6 also attenuated the protective effect of cyclodextrin (CD) on Ang II-induced urinary albumin excretion, glomerulosclerosis and podocyte injury." (PMID 32642006, 2020). "Our results showed that STZ-diabetic ETBR-/- mice enhanced glomerulosclerosis and had higher levels of renal damage signs (serum creatinine and urinary albumin) and increased mRNA and protein levels of ET-1 in vivo." (PMID 30926764, 2019). "Systolic blood pressure, urinary albumin:creatinine ratio and glomerulosclerosis index were all increased in SNx‐E rats compared with sham‐E by 8 weeks postsurgery." (PMID 30575177, 2019).